CDK2 (cyclin dependent kinase 2)
Diseases named in the same sentence as CDK2 in open-access papers (continued):
Sharing a sentence is not in itself a finding about the gene and the disease.
glioma (70 papers, 2008 to 2026). A benign or malignant brain and spinal cord tumor that arises from glial cells (astrocytes, oligodendrocytes, ependymal cells). "For example, a dominant negative KAP variant generated by aberrant splicing dysregulated both Cdk2-dependent proliferation and cdc2-dependent migration and increased malignancy in human gliomas." (PMID 34445990, 2021). "Additionally, we highlighted several protein targets and related pathways linked to glioma, including Vitamin D3 receptor, thyroid hormone receptor, acetylcholinesterase, cyclin-dependent kinase 2, tubulin alpha chain, dihydrofolate reductase and thymidylate synthase." (PMID 40475540, 2025). "As a study has shown, a FAM family member, FAM84B, regulates the proliferation of glioma cells by acting on the cell cycle pathways like CDK2." (PMID 39999107, 2025). "For example, discovering the role of single gene in a single tumor, they argued in detail the identity of SCN3B and CDK2 in glioma, and proved the role of AIMP1, CNIH4 in head and neck squamous cell carcinoma." (PMID 40108724, 2025). "Studies such as those on SCN3B in glioma, CDK2 in glioma, AIMP1 in head-neck squamous cell carcinoma and CNIH4 in head and neck squamous cell carcinoma demonstrate the diverse applications of TCGA data in cancer research." (PMID 40290723, 2025). "The emergence of P129 fills the gap in CDK-2 inhibitors for the treatment of glioma and offers new opportunities to improve the therapeutic outcomes of glioma patients." (PMID 38184514, 2024). "The pyrazole ring-containing isolongifolanone derivate P129 exhibited promising anti-glioma activity by targeting CDK-2 and promoting apoptosis, indicating its potential importance as a new chemotherapeutic option for glioma." (PMID 38184514, 2024). "The CDK-2-targeting and glioma-inhibiting effects of P129 were confirmed using a series of network pharmacological predictions and in vitro experiments." (PMID 38184514, 2024). "The abnormal expression or function of CDK-2 has been shown to be related to a variety of cancers, including glioma." (PMID 38184514, 2024). "We found that CTSB overexpression partially increased CDK2 and CyclinD1 expression in ar-turmerone-treated glioma cells, while it reduced P27 expression." (PMID 37768200, 2023). "Ar-turmerone treatment reduced the expression of CTSB, CDK2 and CyclinD1, but increased the expression of P27 in glioma cells." (PMID 37768200, 2023). "Upregulation of CDK1 promoted oncogenesis and progression of human gliomas, whereas downregulation of CDK1 and CDK2 expression inhibited the migration and invasion of human gliomas." (PMID 34953010, 2022). "Many researchers have demonstrated that CDK2 acts a key role in the proliferation, migration, and invasion of human glioma." (PMID 34556022, 2021). "Meanwhile, VPS25 induced a G0/G1 phase arrest of the cell cycle in glioma cells by directly mediating p21, CDK2, and cyclin E expression, and JAK-signal transducer and activator of transcription (STAT) activation." (PMID 34863175, 2021). "We assessed the protein levels of cdc25A, CDK2, and Cyclin A2 and found that the levels of these three proteins were reduced in glioma cells treated with PTE." (PMID 33737656, 2021). "The mechanisms involved in the suppression of glioma cell growth were blockage of the cell cycle in S phase by inhibition of CDK2/cyclin E1 and promotion of apoptosis through the Bcl-2/Bax pathway." (PMID 33116114, 2020). "The present study revealed that FOXD2-AS1 knockdown inhibits CDK2 activity and up-regulates cyclin E and p21 in glioma cells, indicating its involvement in the regulation of the cell cycle." (PMID 33336050, 2020).
glioma (continued). "Taken together, these results indicate that MPT0B291 inhibited cell proliferation by inducing G1 cell cycle arrest and down-regulating G1/S regulators Cdk2 and Cdk4 in glioma cells." (PMID 33162824, 2020). "Our findings discover that SAE1 overexpression leads to increase of Akt SUMOylation and Akt phosphorylation (Ser473), which increases expression of CDK2, Cyclin D1, Bcl-2 and ultimately to promote glioma cell proliferation and progressin." (PMID 31345225, 2019). "cZNF292 is found to suppress glioma cells proliferation and vascularization by reducing the expression of cellular Cyclin A, p-CDK2, CDK2, β-catenin, p-STAT3(Tyr705) and p-STAT5 (Tyr694)." (PMID 28969093, 2017). "Taken together, we propose that HSP90AA1-IT1, a potential oncogenic lncRNA, performs its function in part via regulating miR-885-5p-CDK2 signaling axis, which would provide a new therapeutic perspective on targeting gliomas." (PMID 29088865, 2017). "Jnk3 has been shown to stabilize p27 and led to growth arrest in C6 glioma cells, and so, following this precept, we confirmed that Jnk3‐shRNA down‐regulates p27, enhancing expression of Cdk2 in CMs for proliferation." (PMID 28011860, 2017). "Strikingly when HSP90AA1-IT1 was overexpressed into the glioma cells, the inhibitory effect of miR-885-5p on CDK2 was dramatically reversed, evidently supporting a ceRNA role of HSP90AA1-IT1 in the expression of CDK2." (PMID 29088865, 2017). "Downregulation of cZNF292 inhibits the proliferation and vascularization of glioma cells and reduces the levels of cellular Cyclin A, CDK2, p-CDK2, β-catenin, p-STAT3 (Tyr705) and p-STAT5 (Tyr694)." (PMID 28143578, 2017). "In this study, we showed that over-expression of HOTTIP can inhibit the expression of CDK2 and cyclin A proteins and that over-expression of BRE can enhance the expression of CDK2 and cyclin A proteins in the U87-MG and U118-MG glioma cell lines." (PMID 27733185, 2016). "This would be in line with a previous report showing that BMP7 decreases proliferation of a glioma cell line through cell cycle arrest in the G1 phase, through the modulation of CDK2, CDKN1A and pRB expression." (PMID 25860932, 2015). "Dlk1 expression is increased in gliomas and over-expression in transfected cells promotes cell proliferation by inducing the expression of cyclin D1, CDK2, and E2F4." (PMID 19331679, 2009). "RIPK1 was positively correlated with the expression of cyclin E1 (CCNE1), CDK2, TIMP1, N-cadherin (CHD2), and other genes implicated in glioma proliferation and invasion, whereas MLKL exhibited a weaker or negative correlation with most genes in this signature." (PMID 41429922, 2025). "Finally, we visualized the close association between CDCA3 and common glioma cell cycle checkpoint markers, including CDK6, CDK4, CDK2, CDK1, CDKN3, and CDKN2C, using circos plots." (PMID 38728485, 2024). "The use of CDK-2 inhibitors has the potential to be extended for the treatment of other cancers because many cancers have aneuploid cells with supernumerary centrosomes, which is consistent with the results of glioma cell treatment with P129 in this study." (PMID 38184514, 2024). "DKC1 could upregulate the expression of N-cadherin, MMP-2, HIF1A, CDK2, and cyclin E, and the glioma cells with DKC1 knockdown exhibited low motility." (PMID 36437949, 2022). "In addition, we investigated the potential biological process through which BACE2 promotes glioma malignant development and evaluated the expression levels of some key regulators of the cell cycle, including CDK2, CDK4, cyclin D1, p21 and p27." (PMID 31856384, 2020). "We found that glioma cells after ARG treatment regulated the levels of CDK2 and cyclin E protein." (PMID 33015162, 2020).
glioma (continued). "Altogether, these results suggested that miR-885-5p directly targeted CDK2 in the glioma cells." (PMID 29088865, 2017). "Taken together, it is concluded that HSP90AA1-IT1, performs its function via regulating the development of gliomas through miR-885-5p-CDK2 signaling axis, and this has added new perspective to its role in tumorigenesis, thus providing potential therapeutic targets for glioma treatment." (PMID 29088865, 2017). "Moreover, re-introduction of hsa-miR-524-5p in glioma cells showed that Ttk, Cdk2 and Wee1 expression were reduced in LN229 cells via transfecting hsa-miR-524-5p." (PMID 24194606, 2013). "To identify the molecular mechanisms by which netrin-1 promoted cell proliferation and glioma growth, we examined the expression levels of several key molecules related to cell proliferation and the cell cycle, including c-Myc, cyclin D1, p27, cyclin E and cdk2 in U251 and U87MG cells." (PMID 28710382, 2017). "In addition, a 24 h exposure to CAPE (50 μg/ml) inhibited the growth of C6 glioma cells, inducing cell cycle arrest at the G1 subphase after a 24 h incubation, decreasing the CDK2/cyclin E and CDK4/cyclin D activity and inhibiting Rb phosphorylation by increasing p21, p27 and p16 expression." (PMID 26694491, 2015). "Western blot analysis revealed that ar-turmerone downregulated the G1/S-phase biomarkers Cyclin-dependent kinase 2 (CDK2), CyclinD1 and upregulated P27 in glioma cells." (PMID 37768200, 2023). "NVP-HSP990 disrupted cell-cycle control mechanisms by decreased CDK2 and CDK4 levels and increased glioma tumor-initiating cell apoptosis levels." (PMID 33390934, 2020). "In our study, mRNA level of Cdk2, Cdk4 and Cdk6 down-regulated in MPT0B291-treated glioma cells indicating that HDAC6 inhibitor transcriptionally regulates those cyclin-dependent kinases." (PMID 33162824, 2020). "Knockdown of FOXD2-AS1 in glioma cells significantly inhibited cell proliferation, migration, invasion and epithelial–mesenchymal transition (EMT) and regulated the expression of CDK2, cyclinE1, P21, MMP7 and MMP9." (PMID 33336050, 2020). "Mechanistically, KLHDC8A regulated various functions in glioma by directly mediating Bcl2, BAX, p21, CDK2, MMP2 transcription and ERK and P38 MAPK activation." (PMID 32851798, 2020). "In case of general glioma, top hub nodes included HER2 and HER4 as part of one cluster; as for astrocytoma, the top hub nodes listed CCNE2 and CDK2 as part of one cluster and VEGF and NRP1 as components of another cluster." (PMID 31952211, 2020). "The expression levels of global SUMOylation, SAE1, AKT, p-Akt, Cyclin D1, CDK2, p21, Bcl-2 and active Caspase-3 were increased in the SAE1-overexpressing glioma tissues." (PMID 31345225, 2019).
glioma (continued). "Moreover, to uncover the potential molecular mechanisms by which TAGLN2 promote glioma development, we detect the expression change of FoxM1, an oncogenic transcriptional factor that regulates some key mediators of cell cycle progression, including CDK2, cyclin B1, cyclin D1, p21 and p27." (PMID 29110682, 2017). "In contrast to higher CDK2 immunostaining in the gliomas derived from the cells transduced with scrambled control shRNA, the gliomas depleted of HSP90AA1-IT1 or upregulated with miR-885-5p displayed much lower and more variable levels of CDK2." (PMID 29088865, 2017). "In comparison with Hono or Mag alone, co-treatment with Hono and Mag (Hono-Mag) decreased cyclin A, D1 and cyclin-dependent kinase 2, 4, 6 significantly, leading to cell cycle arrest in U87MG and LN229 human glioma cells." (PMID 27074557, 2016). "Cell cycle progression in human glioma U87MG and U251 cells was halted at S/G2/M phase via the Wnt/β-catenin signaling pathway and related genes such as PRR11, Cyclin A, p-CDK2, VEGFR-1/2, p-VEGFR-1/2 and EGFR." (PMID 27613831, 2016). "The increased expression of tumor-suppressors is common in many cancer types, including cyclin dependent kinase inhibitor p16Ink4a in glioma and HPV-induced cancers, CDK4/6 inhibitor p18Ink4c in cervical cancer and glioblastoma, and CDK2 and PCNA inhibitor p21 in many types of cancer." (PMID 40568073, 2025). "For that purpose, we analyzed two more pediatric glioma tissues, one additional PA (ICGC_PA74, KIAA1549::BRAF fusion) and one pleomorphic xanthoastrocytoma (PXA, a CNS WHO grade 2–3 tumor, I007_024, BRAF V600E and CDK2 NA/B deletion)." (PMID 40229354, 2025). "In this study, the compound P129 was synthesized to target CDK-2, and the cell cycle analysis revealed a significant dose-dependent arrest of glioma cells in the G1, with the absence of S-phase cells." (PMID 38184514, 2024). "Following this point of view, although the results of molecular docking supported the existence of affinity potential of TIZ with CDK1, CDK2, and CDK4, we only performed siRNA targeting CDK1 to verify the inhibitory effect of TIZ on the proliferation of gliomas." (PMID 35694267, 2022). "In this way, to attain the potential molecular mechanisms by which CUL7 promotes glioma development, we detected the expression changes of some key mediators of cell proliferation and apoptosis, including p21, p27, cyclin D1, CDK4, cyclin E1 and CDK2." (PMID 32252802, 2020). "Tyrosine-specific phosphoproteomic analysis of IL-33+ tumors showed an increase in a number of phospho-peptides derived from STAT3, CDK1, CDK2, FYN, MAPK14, and MAPK3, some that based on amino acid sequence could be attributed to either human glioma or mouse host origin." (PMID 33020472, 2020). "In addition to inhibiting CDK7, SNS-032 also inhibits the cyclin-dependent kinases CDK2, CDK5 and CDK9, however, even though SNS-032 can alter glioma response to hypoxia, it is not toxic toward U87 cells even at very high drug concentrations (500 nM)." (PMID 29844863, 2018).
gastric cancer (65 papers, 2008 to 2025). A primary or metastatic malignant neoplasm involving the stomach. "Pyroptosis is also associated with gastric cancer via downregulation of GSDMD accelerating expression of cdk2/cyclin A2 complexes that promote transition from S to G2 phase, thus accelerating gastric cancer cellular proliferation." (PMID 38645692, 2024). "Considering the impact of LETM2 on cell cycle progression in gastric cancer, we conducted Western Blot experiments to evaluate the expression of G0/G1 phase-associated cyclins, CDK2, CDK4, CDK6, CyclinB1, and CyclinE2." (PMID 38654380, 2024). "For example, CDK4/6-inhibitor resistance in human gastric cancer was shown to be associated with the second arm of the cell cycle/RB/E2F pathway – Cyclin E and CDK2." (PMID 30890123, 2019). "PCBP2 associated with CDK2 could be used as a potential biomarker for gastric cancer therapy." (PMID 29744291, 2018). "On the contrary, in gastric cancer, PCBP2 interacts with the 3′UTR region of CDK2 transcript, thereby accelerating the cell cycle of gastric cancer cells and promoting tumorigenesis." (PMID 39366930, 2024). "Bay has been used in experimental models of gastric cancer, where it induced S phase arrest by inhibiting Cyclin A and CDK-2 expression." (PMID 38994944, 2024). "It provides a rationale for the involvement of CDK2 in the development of gastric cancer as a novel upstream factor for gene regulation of CDK2." (PMID 36769170, 2023). "In gastric cancer cell lines, CDK2 modulates the aerobic glycolytic capacity via suppression of SIRT5 which acts as a tumor suppressor in gastric cancer cells." (PMID 36769170, 2023). "Apart from regular cell cycle regulatory pathways, CDK2 is also a major regulator of cancer cell metabolism in gastric cancer." (PMID 36769170, 2023). "Another long non-coding RNA GHET1, which is highly expressed in gastric cancer cells, promotes the cell cycle regulators including CDK2 for inducing the invasive phenotype including the G1-to-S transition and the inhibition of p21." (PMID 36769170, 2023). "The mechanism involves LINC01021-mediated binding of CDX2 and CDK2 to promote angiogenesis, invasion, and migration of gastric cancer cells." (PMID 36769170, 2023). "A long non-coding RNA, GHET1, is upregulated in gastric cancer, and its inhibition in gastric cancer cells leads to reductions in CDK2, Cyclin E1, CDK6, CDK4, and Cyclin D1." (PMID 36769170, 2023). "For example, miR-302b inhibits conversion of the G1/S by negatively regulating CDK2 to inactivate the ERK signaling pathway in gastric cancer." (PMID 35379170, 2022). "In this study, LH was proved to cause cell cycle arrest at S phase and induced apoptosis in gastric cancer by inhibiting MCL1, which is consistent with the previous reports that MCL1 is involved in cell cycle by improving the stability of CDK2 protein." (PMID 33126914, 2020). "1,25(OH)2D3 induced p21 high expression and induced suppression of cyclin dependent kinase 2 (cdk2) expression in TMK1 human gastric cancer cell line." (PMID 32679655, 2020). "For instance, silencing CDK2 attenuated aerobic glycolytic cell metabolism in cells, thereby inhibiting the malignant characterization of gastric cancer cells." (PMID 32699532, 2020). "The growth inhibitory effect of celery seed extracts on human gastric cancer BGC-823 cells caused cell cycle arrest at the S-phase and decreased levels of cyclin A and CDK-2." (PMID 32580345, 2020).